HTT (huntingtin)
Diseases named in the same sentence as HTT in open-access papers (continued):
Sharing a sentence is not in itself a finding about the gene and the disease.
Huntington disease (continued). "attempted to express the expanded CAG repeats in the huntingtin protein responsible for Huntington’s disease (HD), an autosomal dominant neurodegenerative disease, in the photoreceptor neurones of Drosophila by using Glass Multiple Reporter (GMR)-Gal4." (PMID 35765969, 2022). "Huntington’s disease (HD) is a fatal genetic neurodegenerative disease that is directly related to the aggregation of mutant huntingtin (HTT) protein where the expansion of polyglutamine occurs." (PMID 35159390, 2022). "Huntington’s disease (HD) is characterised by an abnormally high amount of polyglutamine (poly Q) in the huntingtin (Htt) protein due to a triple repeat of cytosine, adenine, and guanine (CAG)." (PMID 36359390, 2022). "Here, we review current evidence supporting the existence of prion-like mechanisms in Huntington’s disease (HD), an autosomal dominant neurodegenerative disease caused by expansion of a CAG repeat tract in exon 1 of the huntingtin (HTT) gene." (PMID 36090278, 2022). "Huntington’s disease (HD) is an autosomal dominant, neurodegenerative disorder caused by a trinucleotide (CAG) repeat expansion in the huntingtin (HTT) gene." (PMID 35207493, 2022). "Huntington’s disease (HD) is a late-onset lethal dominant genetic disorder due to a CAG repeat within exon 1 of the Huntingtin (Htt) gene." (PMID 35213386, 2022). "Extended CAG trinucleotide repeats (TNR) in the genes huntingtin (HTT) and androgen receptor (AR) are the cause of two progressive neurodegenerative disorders: Huntington’s disease (HD) and Spinal and Bulbar Muscular Atrophy (SBMA), respectively." (PMID 36585400, 2022). "Huntington’s disease (HD) is an autosomal dominant neurodegenerative condition in which mutant Huntingtin protein (Htt) accumulates in the nucleus." (PMID 36092728, 2022). "Huntington’s disease (HD) is an autosomal, dominant, neurodegenerative illness resulting from a CAG repeat mutation on exon-1 of the Huntingtin gene (HTT)." (PMID 35631226, 2022). "Huntington’s disease (HD) is an autosomal dominant neurodegenerative disorder that occurs due to abnormal expansion of the CAG repeat sequence in the exon 1 of the HTT gene." (PMID 36209136, 2022). "By contrast, Huntington’s disease (HD) is a central nervous system cognitive and motor disorder caused by an expanded number of CAG repeats in the huntingtin (HTT) gene." (PMID 35326500, 2022). "Diseases in this group include Huntington's disease (HD), caused by expansion of CAG/CTG-STR in the first exon of the huntingtin (HTT) gene (Ref." (PMID 36059110, 2022). "Huntington’s disease (HD) is an autosomal dominant ND with an average onset age of 40 years, characterized by expansion of polyglutamine repeats in the protein called huntingtin (htt)." (PMID 35204286, 2022). "Huntington’s disease (HD) is a neurodegenerative disease that is caused by the expansion of CAG repeats, encoding polyglutamines, in the gene huntingtin." (PMID 36009188, 2022). "The most significantly affected pathway was the Huntington’s disease signaling pathway, which, along with huntingtin (HTT) protein, was down-regulated by Posiphen in the SH-SY5Y cells." (PMID 34959389, 2021). "Huntington’s disease is the most common inherited neurodegenerative disease and is caused by CAG repeat expansion in the first exon of Huntingtin (HTTex1,)." (PMID 34160773, 2021). "Oppositely, in a range of 6.25–100 μM Mn was shown to induce autophagic flux in Huntington’s disease cell models resulting in autophagic sequestration of huntingtin (Htt) aggregates, thus possessing protective effect." (PMID 33925013, 2021). "In this study, we have applied HTRF, AlphaLISA and MSD assays to detect soluble and aggregated HTT isoforms in brain tissues from zQ175 mice, the most commonly used knock-in mouse model of Huntington’s disease." (PMID 33604571, 2021).
Huntington disease (continued). "Huntington’s disease (HD) is a devastating neurodegenerative disorder, caused by a CAG/polyglutamine repeat expansion, that results in the aggregation of the huntingtin protein, culminating in the deposition of inclusion bodies in HD patient brains." (PMID 33907289, 2021). "Huntington's disease (HD) is an autosomal dominant disease caused by a cytosine, adenine, and guanine (CAG) repeat expansion in the gene that encodes huntingtin (HTT)." (PMID 34025560, 2021). "They show that the abundance of HAP40 is coupled with that of HTT and that there is greater conformational variety in the exon 1 of the mutant HTT than WT, important for the future drug discovery studies targeting Huntington’s disease." (PMID 34880419, 2021). "In Huntington’s disease, mutant huntingtin aggregates are transferred between cells by several routes." (PMID 35069097, 2021). "The first exon of the huntingtin protein (HTTex1) important in Huntington’s disease (HD) can form cross-β fibrils of varying toxicity." (PMID 34257293, 2021). "Huntington’s disease is a rare genetic neurodegenerative disease in which the Huntingtin (HTT) has an abnormal expansion of 40 or more CAG trinucleotide repeats." (PMID 33889597, 2021). "Huntington’s disease (HD; OMIM #143100) is a fatal inherited neurodegenerative disorder caused by autosomal dominant mutation in the huntingtin (HTT) gene." (PMID 34518368, 2021). "Huntington’s disease (HD) is a well-studied example of a TNR progressive neurodegenerative disorder, caused by expansion of CAG repeats in the huntingtin (HTT) gene, in which the expansion length determines the age of onset." (PMID 34869348, 2021). "Aggregates of polyglutamine-expanded huntingtin are found within genetically normal tissue grafted into patients with progressing Huntington’s disease, indicating cell-to-cell transit of huntingtin aggregates in vivo." (PMID 35069097, 2021). "Neurodegenerative diseases, such as AD, Parkinson’s disease, Huntington’s disease, multiple sclerosis, and prion-like diseases, are characterized by the deposition of misfolded proteins, such as Aβ, tau, α-synuclein, huntingtin, and prion proteins." (PMID 34744633, 2021). "It is also an eQTL of F8, and F8A1 (DXS522E/HAP40), a likely candidate for the aberrant nuclear localisation of mutant huntingtin in Huntington’s disease." (PMID 33875891, 2021). "Huntington’s disease is an autosomal, dominant inherited disorder related to the presence of a defective huntingtin gene (Htt)." (PMID 34069559, 2021). "These selected assays can be used to compare the levels of huntingtin protein isoforms in a wide variety of mouse models of Huntington’s disease and to determine how these change in response to genetic or therapeutic manipulations." (PMID 33604571, 2021). "Antagonizing the pathogenic overexpression of SERPINA1 in neurons and glia mitigates mutant Huntingtin (mHTT)-induced behavioral impairments and lowers mHTT protein levels in Drosophila and Huntington's disease (HD) mouse striatal cells." (PMID 33871358, 2021). "Huntington’s Disease (HD) is a progressive, genetic neurodegenerative disorder caused by unstable CAG repeat expansions in the first exon of the Huntingtin gene (HTT)." (PMID 33940564, 2021). "Clusters of concordant differentially expressed genes (DEGs) between human and mouse Huntington's disease (HD) striata and Drosophila expressing mutant Huntingtin (mHTT) in glia." (PMID 33871358, 2021). "An example is the drug targeting HTT in Huntington’s disease, which use ASO to decrease the levels of the mutant huntingtin protein (mHTT)." (PMID 33513969, 2021). "Mutations in the huntingtin gene (HTT) triggers aggregation of huntingtin protein (mHTT), which is the hallmark pathology of neurodegenerative Huntington’s disease (HD)." (PMID 34924935, 2021). "Huntington's disease (HD) is a progressive and fatal autosomal dominant neurodegenerative disease caused by a CAG repeat expansion in the first exon of the huntingtin gene (HTT)." (PMID 33918672, 2021).
Huntington disease (continued). "BDNF function is reduced in Huntington’s disease (HD), possibly because mutant huntingtin impairs its cortico-striatal transport, contributing to striatal neurodegeneration." (PMID 33568689, 2021). "Huntington’s disease (HD) is caused due to the expansion in CAG repeat in the exon 1 of the huntingtin gene, which translates into a polyglutamine (polyQ) tract in the huntingtin (Htt) protein." (PMID 33525374, 2021). "Significantly, clinical trials have been conducted in patients using ASOs targeting superoxide dismutase 1 (SOD1) in ALS and the mutant huntingtin gene in Huntington’s disease." (PMID 34054431, 2021). "Huntington’s disease (HD), an autosomal dominant neurodegenerative disease caused by CAG repeat expansions in the exon I of the Huntingtin (HTT) gene, is characterized by progressive psychiatric, motor, and cognitive symptoms and is fatal." (PMID 33679321, 2021). "This specificity would respect other naming conventions, such as Lewy-body dementia, which is defined by the buildup of α-synuclein, and Huntington’s disease, which is defined by the build-up of huntingtin." (PMID 34640387, 2021). "Here the authors describe the discovery of a class of small molecule splicing modifiers which are orally bioavailable, cross the blood-brain barrier, and lower levels of huntingtin in a mouse model of Huntington’s disease (HD)." (PMID 34911927, 2021). "Over this age range, the levels of soluble mutant HTT are known to decrease, and aggregated HTT to increase in the cortex of Huntington’s disease knock-in models." (PMID 33604571, 2021). "In neurons, imbalanced acetylation can result in the toxic build-up of proteins such as tau (Alzheimer’s disease), alpha-synuclein (Parkinson’s disease), huntingtin (Huntington’s disease) and superoxide dismutase 1 (ALS)." (PMID 33483607, 2021). "Huntington's disease (HD) is a rare, genetic, neurodegenerative disease caused by a cytosine adenine guanine (CAG) repeat expansion variant of the huntingtin gene (HTT) and is characterised by a triad of cognitive, behavioural, and motor symptoms." (PMID 34093422, 2021). "These include α-synuclein for Parkinson’s disease and related synucleinopathies, TDP-43 for amyotrophic lateral sclerosis and frontotemporal dementia, as well as mutant huntingtin in Huntington’s disease and poly-Q aggregates in spinocerebellar ataxias." (PMID 33846962, 2021). "These have included homogeneous time-resolved fluorescence assays (HTRF, also termed TR-FRET) that detect soluble mutant HTT, both soluble mutant and wild-type HTT and aggregated HTT in cultured cells and tissues from mouse models of Huntington’s disease." (PMID 33604571, 2021). "Using this approach, we silenced the huntingtin gene in the brain of a Huntington’s disease mouse model after intravenous administration." (PMID 34795295, 2021). "The injection of an LV carrying SpCas9 nuclease and a sgRNA targeting the huntingtin coding sequence in the striatum of a mouse model of Huntington disease (HD) resulted in a robust knock-down of the mutant hHTT-82Q protein in both neurons and astrocytes." (PMID 34713256, 2021). "Summary: 2D gastruloids of isogenic human embryonic stem cells modeling Huntington's Disease reveal that huntingtin CAG expansion perturbs the spatial restriction of the activin response in the context of the polarized epithelium." (PMID 34608934, 2021). "The reduction in the number of huntingtin aggregates is correlated with an improvement in cognitive and behavioral function in mouse models of Huntington’s disease." (PMID 34069559, 2021). "The targeting sequence used in these experiments has homology among mice, sheep, NHPs, and humans, and it targets huntingtin, the gene involved in Huntington disease." (PMID 34935646, 2021).
Huntington disease (continued). "Such vesicles efficiently deliver siRNA to multiple anatomical regions of the brain in a Huntington’s disease mouse model after systemic injection, resulting in silencing of the huntingtin gene in different regions of the brain." (PMID 34795295, 2021). "A similar observation was made in a study investigating the function of the Huntington's disease protein HUNTINGTIN during heat stress." (PMID 34249042, 2021). "For instance, Huntington’s Disease (HD), which is caused by polyglutamine-encoding CAG expansions in the first exon of the HUNTINGTIN (HTT) gene, is mainly characterized by loss of spiny motor neurons in the striatum, a ventral brain structure." (PMID 34602979, 2021). "In a mouse model of Huntington’s disease (HD), one study showed that sustained activation of IRE1 can trigger neuronal loss, whereas expression of XBP1s decreased aggregation of mutant huntingtin in the striatum." (PMID 34229656, 2021). "Again, in Huntington’s disease (HD), an expansion of the CAG repeat is the cause of the presence of a polyglutamine tract (Ploy-Q) in the huntingtin protein (Htt), which promotes its aggregation." (PMID 34208561, 2021). "Huntington disease (HD) is a devastating neurodegenerative disorder characterized by aggregation of huntingtin (HTT) protein containing expanded polyglutamine (polyQ) tracts." (PMID 34755099, 2021). "Huntington’s disease (HD) is caused by an expansion mutation of a CAG repeat in exon 1 of the huntingtin (HTT) gene, that encodes an expanded polyglutamine tract in the HTT protein." (PMID 34659371, 2021). "Huntington’s disease (HD) is a progressive neurodegenerative disorder that is inherited primarily due to an abnormal CAG repeat expansion of the huntingtin (HTT) gene." (PMID 33946468, 2021). "Huntington’s disease (HD) is a monogenetic neurodegenerative disorder characterized by the accumulation of polyglutamine-expanded huntingtin (mHTT)." (PMID 33809220, 2021). "Huntington’s disease (HD) is a rare neurodegenerative disorder, caused by an expansion of CAG trinucleotide repeats in the huntingtin (HTT) gene, which is located at chromosome 4p16.3." (PMID 34393630, 2021). "Huntington disease (HD) is a neurodegenerative, fatal trinucleotide repeat disorder caused by a CAG expansion in exon 1 of the huntingtin gene (HTT) yielding a mutant protein (mHTT) with a polyQ tract exceeding a pathogenic threshold of Q > ~351." (PMID 34239038, 2021). "Huntington’s disease results from expansion of a glutamine-coding CAG tract in the huntingtin (HTT) gene, producing an aberrantly functioning form of HTT." (PMID 34880419, 2021). "Huntington disease (HD) is a rare, autosomal dominant neurodegenerative disorder caused by the abnormal expansion of a CAG repeat sequence in the Huntingtin (HTT) gene." (PMID 33568143, 2021). "Huntington’s disease (HD) is a monogenic neurodegenerative condition arising due to inheritance of ≥36 CAG repeats in exon 1 of the huntingtin (HTT) gene." (PMID 34469738, 2021). "Visual deficit is one of the complications of Huntington disease (HD), a fatal neurological disorder caused by CAG trinucleotide expansions in the Huntingtin gene, leading to the production of mutant Huntingtin (mHTT) protein." (PMID 34884576, 2021). "Transcriptional and cellular-stress surveillance deficits are hallmarks of Huntington’s disease (HD), a fatal autosomal-dominant neurodegenerative disorder caused by a pathological expansion of CAG repeats in the Huntingtin (HTT) gene." (PMID 34880223, 2021). "To assess the silencing efficiency and therapeutic potential of G58TF/siRNA-RVG-EVs in the brain, we targeted silencing of the huntingtin gene (Htt) in the Huntington’s disease (HD) mouse model Q14054." (PMID 34795295, 2021). "The key marker for Huntington disease (HD), huntingtin (htt), is normally palmitoylated at Cys214 by huntingtin interacting protein 14 (HIP14), a palmitoyltransferase also known as ZDHHC17." (PMID 33430908, 2021).
Huntington disease (continued). "Huntington’s disease (HD) is a fatal neurodegenerative disorder due to an extraordinarily expanded CAG repeat in the huntingtin gene that confers a gain-of-toxic function in the mutant protein." (PMID 34899193, 2021). "Neuropathologic hallmarks of Huntington Disease (HD) include the progressive neurodegeneration of the striatum and the presence of Huntingtin (HTT) aggregates that result from abnormal polyQ expansion of the HTT gene." (PMID 33517535, 2021). "Huntington’s disease (HD) is a representative neurodegenerative disease, caused by excessive triplet (CAG) repeat located in huntingtin (HTT) gene on chromosome 4 that codes for polyglutamine in the huntingtin protein." (PMID 34433483, 2021). "Meanwhile, Huntington’s disease (HD) is a representative neurodegenerative disease, which is caused by a triplet (CAG) repeat elongation in huntingtin (HTT) gene on chromosome 4 that codes for polyglutamine in the huntingtin protein." (PMID 34465339, 2021). "Among these, Huntington’s disease (HD) is an autosomal dominant ND generated by the CAG expansion in the first exon of the Huntingtin gene resulting in a protein with an abnormally long polyglutamine sequence." (PMID 32526949, 2020). "Huntington’s disease (HD), also called Huntington’s chorea, is a genetic, autosomal dominant disease, caused by the expansion of a trinucleotide sequence (CAG) in exon 1 of the huntingtin gene." (PMID 32046139, 2020). "Huntington’s disease (HD) is an inherited, progressive neurodegenerative disorder caused by a CAG repeat expansion in the 5′ coding region of the Huntington (HTT) gene." (PMID 32194366, 2020). "Huntington’s disease (HD) is caused by a CAG triplet repeat expansion, encoding polyglutamine (polyQ), in the huntingtin (HTT) gene on chromosome 41." (PMID 32555394, 2020). "p62 is known to regulate the aggregation and degradation of proteins associated with neurodegenerative disease including alpha-synuclein as well as tau (which aggregates in Alzheimer’s disease), and huntingtin (which aggregates in Huntington’s disease)." (PMID 32850835, 2020). "It has also been demonstrated that the compound inhibits huntingtin aggregation in vitro, increases the survival rate of mutant huntingtin transduced primary neuron culture and shows a positive effect in Huntington’s disease models in vivo." (PMID 32864220, 2020). "Huntington’s disease (HD) is a heritable, neurodegenerative disorder, caused by an unstable trinucleotide (CAG) repeat expansion in exon 1 of the huntingtin gene on the short arm of chromosome 4." (PMID 32164608, 2020). "Orally dosed VCE‐003.2 (10 mg·kg−1) promoted neurogenesis in mice subjected to mutant Huntingtin expression in a Huntington's disease model." (PMID 32608035, 2020). "Proteotoxic aggregates in neuronal cells of Huntington’s disease (HD) patients are formed by N-terminal polyglutamine (polyQ)-expanded huntingtin (HTT)." (PMID 32858836, 2020). "In Huntington's disease, mutant huntingtin protein induces oxidative stress to lead to aberrant activation of AMPKα1 and neuronal atrophy." (PMID 32377295, 2020). "CRYM (Ketimine‐reductase mu‐crystallin) has been reported as a modulator of huntingtin toxicity to striatal neurons in Huntington's disease." (PMID 32485097, 2020). "Huntington’s disease (HD) is a fatal autosomal dominant neurodegenerative disorder, caused by a CAG-triplet repeat expansion in the gene IT15 encoding the protein huntingtin." (PMID 32493491, 2020). "For example, in Huntington disease, expression of a huntingtin (HTT) isoform containing exon 1 alone with the CAG repeat produces a highly toxic and aggregate-prone factor that accumulates in patient brains." (PMID 32753055, 2020). "The huntingtin (HTT) protein in its mutant form is the cause of the inherited neurodegenerative disorder, Huntington’s disease." (PMID 33057179, 2020).